MERTK (MER proto-oncogene, tyrosine kinase)
Diseases named in the same sentence as MERTK in open-access papers (continued):
Sharing a sentence is not in itself a finding about the gene and the disease.
tumor (continued). "Nevertheless, MerTK may be seen as a double-edged sword, as it modulates the immune system by reducing immune cell activation through the clearance of ACs, but it has also been implied to have tumour-intrinsic functions due to its aberrant expression on several types of cancerous cells." (PMID 36555321, 2022). "The MERTK pathway was also activated in EGFRMT tumor xenografts in response to treatment with OSI, consistent with a role for MERTK in OSI resistance in vivo." (PMID 35708914, 2022). "MERTK inhibition using shRNA or a MERTK kinase inhibitor reduced NSCLC colony formation in vitro and xenograft tumor growth in vivo." (PMID 35708914, 2022). "The genetic depletion of MERTK or inhibition of MERTK by UNC2025 reduced the number of macrophages in tumors and sensitized the response of tumor cells to radiotherapy." (PMID 33562150, 2021). "Axl-/-/MerTK-/- macrophages express higher levels of the pro-inflammatory cytokines TNF-α and IFN-γ, triggering tumor-promoting inflammation." (PMID 34771611, 2021). "Expression of MERTK and AXL on tumor-infiltrating macrophages polarizes them towards a pro-tumor M2-like phenotype." (PMID 34830794, 2021). "We found that several pro-tumor markers are increased in cancer tissues, including CD163, CD206, SIRPα, LILRB1, SIGLEC10, AXL, MERTK, and MARCO." (PMID 34778091, 2021). "In TAMs compared to non-tumor macrophages, MMP12, a protease involved in macrophage migration and the regulators of lymphocyte homing and inflammation ENPP2, MERTK and F13A1 were upregulated." (PMID 33918618, 2021). "Interestingly, treatment of the MERTK monoclonal antibody has a limited effect on the bacteria-induced inflammatory response in macrophages, suggesting that MERTK plays a unique fundamental role in the tumor microenvironment, in addition to its role in systematic inflammation." (PMID 33562150, 2021). "Many cancers have been found to express MERTK or another TAM receptor, through which they clear dying tumor cells." (PMID 34065321, 2021). "Here we demonstrate that INCB081776, currently in phase 1 clinical trials, is a highly selective inhibitor of AXL and MERTK and functions to inhibit AXL and MERTK through immunomodulatory as well as tumor-directed signaling mechanisms." (PMID 33425754, 2020). "The pattern of expression of cellular markers (CD11b, MERTK, F4/80, Arginase-1 and CD206) is consistent with the generation of M2 macrophages in response to tumor cell-derived exosomes." (PMID 32456301, 2020). "TYRO3, AXL, and MERTK constitute the TAM family of receptor tyrosine kinases, which play important roles in tumor growth, survival, cell adhesion, as well as innate immunity, phagocytosis, and immune-suppressive activity." (PMID 33425754, 2020). "After LLC cell injection, we treated mice with a MerTK inhibitor (Foretinib), an NF-κB inhbitior (Bay 11-70852), or both, beginning at day 6 after LLC injection (when the tumor size reached 50-100 mm3)." (PMID 31903163, 2019). "It has been shown that Protein S activation of either MerTK or Tyro3 inhibits LPS and IFN-γ induced M1 polarization of peritoneal and tumor-derived mouse macrophages, indicated by decreased expression of M1 marker genes Il1, Il6, Cd86 and Tnf." (PMID 31088471, 2019). "MerTK is expressed by many tumors, including NSCLC, and receptor blockade has been shown to reduce tumor growth, consistent with our findings." (PMID 31903163, 2019). "For example, recent findings indicate roles for MerTK, MFG-E8, and PtdSer in the development and progression of neoplasia specific to their efferocytic functions." (PMID 30187085, 2018). "Co-targeting MerTK and BRAFV600 significantly reduced tumour burden in xenografted mice, which was pheno-copied by co-inhibition of autophagy and mutant BRAFV600." (PMID 29050198, 2017). "Long-term treatment with PLX and CQ abolished tumour regrowth compared with single treatment with PLX, which was pheno-copied by single PLX treatment combined with MerTK depletion." (PMID 29050198, 2017).
tumor (continued). "It has been shown that one of the first reported MerTK inhibitors, UNC1062, inhibited MerTK phosphorylation and cell proliferation in different tumor cell lines." (PMID 29285287, 2017). "Taken together, we are the first to show that MERTK is frequently overexpressed in HNSCC and plays an important role in tumor cell motility." (PMID 27081701, 2016). "We have previously demonstrated that MERTK activates migratory, survival, and proliferative pathways and is critical to GBM tumor growth." (PMID 27783662, 2016). "Taken together these data suggest an important role for MERTK in HNSCC especially for migration and invasion of tumor cells." (PMID 27081701, 2016). "This line of reasoning led us to investigate the relationship between GAS6 expression, which would be expected to impact signaling through both MERTK and AXL, and tumor progression in GBM using the TCGA database." (PMID 27783662, 2016). "MERTK, a member of the TAM family of RTKs, is expressed in ~90% of GBM tumor samples and the majority of GBM cell lines." (PMID 27783662, 2016). "In vivo and human clinical data suggest that tumor-bound MerTK expression is independent of PD-L1 expression in TNBC." (PMID 40391157, 2025). "The research has demonstrated that inhibiting MERTK reduces the presence of PD-L1 in the TME, thereby limiting tumour cells' ability to elude the immune system.Various tumour cells predominantly express PD-L1 on their surface, while immune cells like DCs and macrophages commonly detect PD-L2." (PMID 40088262, 2025). "Though often overlooked, PD-L1 has several tumor intrinsic functions that have recently been identified to regulate mTOR/AKT, MAPK, STAT3/Caspase 7, integrin β4, MerTK, and BIM/BIK signaling, among others." (PMID 39663510, 2025). "It is critical to ensure that tumor-bound MerTK and PD-L1 expression are not coupled to propose tumor-bound MerTK as an independent biomarker to PD-L1." (PMID 40391157, 2025). "Furthermore, increased levels of cytotoxic granules (Granzyme B and Perforin), anti-tumor cytokines (IFN-γ and TNFα), and the apoptotic marker CHOP/GADD153 were observed in MerTK-overexpressing tumors in both ICI treatment groups by IHC." (PMID 40391157, 2025). "In this study, we observed that STK38 promoted Ras-induced cell migration and tyrosine phosphorylation of MerTK, suggesting that STK38 is most likely involved in Ras-induced cell migration and may facilitate tumor metastasis." (PMID 41226428, 2025). "Unlike CAR-T or CAR-NK cells, CAR-Ms directly engulf tumour cells via FcRγ, Megf10, or MerTK signalling upon antigen recognition." (PMID 40624498, 2025). "Additionally, MERTK expression in epithelial cells overlaps with several tumor epithelial cell clusters, indicating that progressive PTC is more likely to receive signals from the upstream TAM pathway due to elevated MERTK expression." (PMID 40433916, 2025). "Some more research has shown that MERTK, AXL, and other TAM receptors may help the immune system work better by using natural processes inside tumour cells, like making more PD-L1 appear on tumour cells." (PMID 40088262, 2025). "In addition, analysis of 115 primary TNBC tumor samples from TCGA showed a positive correlation (Spearman’s rank correlation coefficient = 0.234, p-value = 0.012) between ENG and MerTK RNA levels." (PMID 38791148, 2024). "This phenotype was mimicked in mice lacking MERTK in macrophages, suggesting that PS/MERTK signaling was needed for macrophage proliferation and subsequent support of tumor growth." (PMID 38573347, 2024). "Additionally, we discovered that MerTK ASO, in conjunction with chemotherapy, MEK inhibitor (AZD6244) and anti-PDL1, and anti-PD1 improves tumor control in various tumor models." (PMID 38443968, 2024). "Although MerTK is absent from normal B and T lymphocytes, it is highly expressed in activated B and T lymphocytes in the tumor microenvironment." (PMID 38341954, 2024).
tumor (continued). "In the primary tumors, MerTK alone produced significant elevation in the percentage of granzB+CD8+ T cells compared to the control mice, but there was no significant change between any of the other treatment groups within the primary tumor." (PMID 38443968, 2024). "In addition, ERO1A, PKP2, and MERTK have been proved to promote the progress and drug resistance of NSCLC by enhancing the activation of tumor and PI3K, EGFR, and other signal pathways." (PMID 37101691, 2023). "Notably, MDK/LRP1, MDK/ALK, GAS6/MERTK, and GAS6/AXL between fibroblasts and tumor cells exhibited a higher communication possibility than that between fibroblasts and thyrocytes." (PMID 37733241, 2023). "Additionally, in a lung adenocarcinoma mouse model, MerTK inhibition in combination with anti-PD1 and radiotherapy has been shown to decrease tumor growth and lead to an abscopal effect." (PMID 37644281, 2023). "Taken together, our findings indicate that the universality of improving anti-tumor immunity through targeting MERTK, irrespective of the tumor model employed, has to be questioned." (PMID 35969037, 2022). "Following the co-expression and network analyses, this signature was found to be enriched for genes involved in the regulation of the stroma component of the tumor (TDO2, STEAP1) as well as Treg cells (SLC16A1, PRKAB1) and myeloid cell (APOBEC3A, MERTK, SNX29) subsets." (PMID 36216827, 2022). "Aberrant expression of MERTK, another TAM RTK, also contributes to chemotherapy resistance, colony-forming potential, migration, EMT induction and involves in main process of anti-tumoral immunity in tumor cells." (PMID 36341335, 2022). "As many cancer types express MERTK and TYRO3 as well as their ligand PROS1, we hypothesized that tumor cells may exploit the TAM-receptor-dependent regulation of osteoblasts and inhibit their function via MERTK39–45." (PMID 36509738, 2022). "Recent studies also suggest that TAM receptors, such as MERTK and AXL may contribute to immunosuppression through cancer intrinsic mechanisms, such as increased PD-L1 expression on tumor cells." (PMID 35572601, 2022). "In human T-cell lymphoblastic leukemia cell lines, the stimulation of MERTK by the ligand Gas6 led to activation of the prosurvival proteins ERK1/2 and MERTK-dependent activation of the STAT pathway and contributed to prosurvival phenotypes of tumor cells." (PMID 33562150, 2021). "Inhibition of MERTK in NSCLC cell lines with a small molecule MERTK tyrosine kinase inhibitor (TKI), MERTK-specific blocking monoclonal antibody, or shRNA induced apoptosis and decreased colony formation in vitro and inhibited tumor growth in vivo." (PMID 34830794, 2021). "However, in a recent animal study of triple-negative breast cancer, the combination of the MERTK inhibitor BMS-777607 and an anti-PD-1 monoclonal antibody synergistically decreased tumor growth and the incidence of lung metastasis." (PMID 33562150, 2021). "Activation of MerTK signaling by its ligands Growth Arrest-Specific 6 (Gas6) and Protein S1 (PROS1) promoted cell proliferation and metastasis and suppressed the immune response in tumour microenvironment." (PMID 33139930, 2021). "Accompanying this were significant changes in regulators of inflammation that were consistent with a shift from AXL to MERTK signaling, which have been distinguished in carefully controlled studies that refine our understanding of TAM receptor signaling in tumor immune surveillance." (PMID 34292953, 2021). "In addition, inhibitors of MERTK MRX-2843 and RXDX-106 have been shown to promote anti-tumor immune responses in vivo in mice." (PMID 34835225, 2021). "Adding anti-PD1 and anti-MerTK to radiation could significantly upregulate CD8+CD103+TRM at the abscopal tumors, suppress the abscopal tumor growth and extended the survival rate." (PMID 34707601, 2021).
tumor (continued). "Moreover, treatment with MERTK kinase inhibitor MRX-2843 re-sensitized resistant cells to osimertinib in cell-based assays and provided durable tumor regression in a mtEGFR NSCLC xenograft model, even after treatment ended." (PMID 34830794, 2021). "Extracellular domains of MERTK and AXL fused to the Fc domain of immunoglobulin G1 can also titrate GAS6 and thereby block GAS6-dependent signaling through the TAM kinases, resulting in decreased tumor metastasis." (PMID 34830794, 2021). "Interestingly, the phagocytosis of apoptotic cells is mediated by MERTK in macrophages and DDR1 induces apoptosis through the upregulation of pro-apoptotic tumor suppressors." (PMID 34830178, 2021). "MerTK is capable of bypassing the blocked cascades, thereby rescuing cells from the anti-oncogenic treatment, and in consequence, dual therapy with either EGF-R or NFκB plus MerTK inhibitors strongly reduced viability and tumor growth." (PMID 34771611, 2021). "Surely, if this is not the case, this important role of MerTK in human T cells would not be illuminated in mouse tumor models." (PMID 33801886, 2021). "Similar to BL2 xenografts in mice, immunohistochemical expression of murine MERTK in MycEd1 tumors was mainly by stromal cells, notably SS-TAMs, rather than by the tumor cells themselves." (PMID 32973744, 2020). "T cells lacking PD-1 upon MERTK-inhibition are therefore likely to be less activated, non-tumor-reactive and correspondingly, less likely to respond to PD-1 immunotherapy." (PMID 31664482, 2020). "MerTK expression on activated B and T lymphocytes suggests that the presence of TAM-R ligands in tumor microenvironment which are produced by myeloid cells might have a functional paracrine effect on infiltrating lymphoid cells." (PMID 33101282, 2020). "In addition, MerTK is a strong inducer of chemokines such as IL-8 and can activate FAK phosphorylation and recruitment to αvβ5 integrin, which is important for tumor cell migration." (PMID 31903163, 2019). "Thus, MERTK function within the immune compartment of the TME suppresses host antitumor immunity, generating a tumor-supportive milieu." (PMID 31775787, 2019). "Merestinib is a potent inhibitor of NTRK, it also targets additional kinases such as the TAM receptors (AXL, MERTK, and TYRO3), and MKNK1 and MKNK2, which may also contribute to anti-tumor growth." (PMID 30885237, 2019). "Thus, tumor cells produce PROS1 in response to pro-inflammatory M1 cytokines and PROS1 stimulates TYRO3 and MERTK on macrophages to promote an anti-inflammatory M2 phenotype, thereby repressing the innate immune response in the tumor microenvironment." (PMID 30501104, 2018). "shRNA-mediated MerTK knockdown or a series of MerTK-selective small molecular inhibitors, such as UNC1062, UNC569, and UNC2025, reduces activation of downstream signaling, inhibits proliferation and invasion, and promotes apoptosis in tumor cells." (PMID 29554921, 2018). "It is important to point out that while merestinib is a potent inhibitor of NTRK, it also targets additional kinases such as the TAM receptors (AXL, MERTK, and TYRO3), and MKNK1 and MKNK2, which may also contribute to anti-tumor growth." (PMID 29568395, 2018). "More importantly, to fully elucidate the biological function of MERTK in metastatic HNSCC and to evaluate its potential as a target, in-vivo experiments with e.g. orthotopic mouse models that more closely resemble the tumor microenvironment would be preferable." (PMID 27081701, 2016). "In summary, these data show that MERTK is frequently overexpressed in HNSCC and might be a potential target for this tumor entity." (PMID 27081701, 2016). "MERTK is a promising therapeutic target in several tumor entities, however, its role in HNSCC has not been described yet." (PMID 27081701, 2016). "Here we investigate whether a novel MERTK-selective small molecule tyrosine kinase inhibitor, UNC2025, has similar anti-tumor effects in GBM cell lines." (PMID 27783662, 2016).
tumor (continued). "Our data indicates MERTK to be a potential target in HNSCC that prevents metastatic spread rather than proliferation of main tumor lesions." (PMID 27081701, 2016). "Interestingly, also a number of oncogenes is up regulated by E2 (MERTK, RET and its ligand ARTN), and several (putative) tumor suppressor genes are down regulated by E2 (BLNK, LATS2, RPRM) that are not, or less, regulated by EGF." (PMID 24758408, 2014). "Foretinib very effectively targets MerTK activation in vivo as evidenced by the immunoblot showing significantly inhibited MerTK phosphorylation in the treated tumor as opposed to the vehicle treated tumor." (PMID 24658326, 2014). "In addition to macrophages, MERTK also affects the function of other immune cells in the TME, including myeloid-derived suppressor cells (MDSCs) and NK cells, which play a crucial role in evading the immune response against tumours." (PMID 40088262, 2025). "Finally, while studies have shown that stromal MerTK and PD-L1 expression are coupled in different cell types, we report that expression of tumor-bound MerTK is not coupled to stromal PD-L1 expression in TNBC." (PMID 40391157, 2025). "However, EMT6 MerTK C5 tumors on mice fed dox chow to induce MerTK expression exhibited significant and strikingly delayed tumor growth starting at day 23 post-inoculation (12 days on dox) compared to both EMT6 Vector + dox and EMT6 MerTK C5 mice fed a regular diet." (PMID 40391157, 2025). "Thus, our preclinical findings identify tumor-bound MerTK as a promising candidate for a biomarker, independent of PD-L1 expression, to predict TNBC response to immune checkpoint therapy." (PMID 40391157, 2025). "Moreover, blocking MerTK, other TAM receptors, or their ligands may result in excessive inflammation and the evasion of tumor cells from undergoing apoptosis." (PMID 41195524, 2025). "Meanwhile, apoptotic tumor cells display “eat-me” signals such as phosphatidylserine and calreticulin, which are recognized by receptors in macrophages responsible for efferocytosis, such as milk fat globule-epidermal growth factor-factor 8 (MFGE8), MerTK, Axl, and Tyro3." (PMID 38802814, 2024). "However, within the primary tumor, other than a slight increase in TH1 cells in mice treated with RCM, there was no additional activation of any immune pathways gained from adding the MerTK ASO to any other therapeutic modality." (PMID 38443968, 2024). "Furthermore, our findings indicate that MerTK ASO can efficiently target TAMs without the necessity for specialized tumor delivery systems like nanoparticles." (PMID 38443968, 2024). "Similarly, TAM receptors (Tyro3, Axl, and MerTK), the cognate receptors of GAS6 on apoptotic cells, are also expressed on TAMs and skew polarization toward a pro-tumor M2-like phenotype, participating in immune homeostasis and tumor progression." (PMID 38274812, 2023). "Although a variety of MerTK targeting therapies are being developed to enhance outcomes for patients with various cancers, the sensitivity of tumors to MerTK suppression may not be uniform due to the heterogeneity of solid tumors and different tumor stages." (PMID 35268561, 2022). "In this review, we present and discuss the role of the TAM family (AXL, MERTK, TYRO3) of receptor tyrosine kinases (RTKs) as a dual target in cancer, due to their intrinsic roles in tumour cell survival, migration, chemoresistance, and their immunosuppressive roles in the tumour microenvironment." (PMID 35626092, 2022). "Despite the enthusiasm, tumor sensitivity to MerTK suppression may not be uniform due to the heterogeneity of solid tumors and different disease stages (for example, primary v." (PMID 35268561, 2022). "The role of MerTK in tumor promoting angiogenesis has not been that clear." (PMID 34771611, 2021).